PTPN12 (protein tyrosine phosphatase non-receptor type 12)
Diseases named in the same sentence as PTPN12 in open-access papers (continued):
Sharing a sentence is not in itself a finding about the gene and the disease.
colorectal cancer (4 papers, 2020 to 2026). A primary or metastatic malignant neoplasm that affects the colon or rectum. "One study presents PTPN12 as a novel candidate that contributes to the heterogeneous susceptibility to colorectal cancer." (PMID 32536826, 2020). "A variant in PTPN12 can increase the risk of colorectal cancer." (PMID 40002844, 2025). "For colorectal cancer (CRC), PTPN2, PTPN21 and PTPN22 levels were correlated with incidence; expression of PTPN5, PTPN12, and PTPN14 was correlated with TNM stage and N stage; high PTPN5 or PTPN7 expression was associated with increased hazards of death." (PMID 32536826, 2020).
esophageal squamous cell carcinoma (4 papers, 2015 to 2022). Esophageal squamous cell carcinoma (ESCC) is a type of esophageal carcinoma (EC) that can affect any part of the esophagus, but is usually located in the upper or middle third. "The miR-940/PTPN12 axis could be a potential drug target to treat esophageal squamous cell carcinoma." (PMID 36556168, 2022). "On the contrary, and without interactions with other overexpressed proteins, PTPN12 (tyrosine-protein phosphatase nonreceptor type 12) is a tumor suppressor protein and has been associated with overall survival in esophageal squamous cell carcinoma patients and non-small-cell lung cancer." (PMID 29744371, 2018). "On the basis of the miR-940/PTPN12 axis, lncRNA GATA2-AS1 restrains esophageal squamous cell carcinoma progression." (PMID 35957898, 2022).
non-small cell lung carcinoma (4 papers, 2015 to 2019). A group of at least three distinct histological types of lung cancer, including non-small cell squamous cell carcinoma, adenocarcinoma, and large cell carcinoma. "High PTPN12 expression was described to be linked with favorable survival duration in non-small cell lung carcinoma patients and with response to neoadjuvant chemotherapy in triple negative breast cancer." (PMID 31606028, 2019). "Tyrosine-protein phosphatase non-receptor type 12 (PTPN12) has been considered to be a tumor suppressor in human cancer, but its clinical and prognostic significance in non-small cell lung cancer (NSCLC) has not been well elucidated." (PMID 25868976, 2015).
ovarian carcinoma (4 papers, 2015 to 2019). A malignant neoplasm originating from the surface ovarian epithelium. "Interestingly, novel data provided further insights on FAK and AKT correlation: in a preclinical model of ovarian cancer, the protein tyrosine phosphatase non-receptor type 12 (PTPN12) dephosphorylates FAK, shutting down the migratory properties." (PMID 28848709, 2017).
prostate carcinoma (4 papers, 2019 to 2023). A carcinoma that arises from epithelial cells of the prostate gland. "PTPN12 expression was analyzed by immunohistochemistry on a tissue microarray with 13,660 clinical prostate cancer specimens." (PMID 31606028, 2019). "Both functional data from prostate cancer cell lines and earlier reports on PTPN12 down regulation in other cancer types suggest a tumor suppressor function of PTPN12." (PMID 31606028, 2019). "This study identifies PTPN12 expression measurement as a valuable prognostic marker in prostate cancer." (PMID 31606028, 2019). "While PTPN1 and PTPN12 were implicated in prostate cancer biology, the involvement of PTPN2 in prostate cancer is not documented." (PMID 37509645, 2023). "PTPN12 analysis, either alone or in combination might be of clinical utility in the prognostic assessment of prostate cancers." (PMID 31606028, 2019). "PTPN12 analysis, either alone or in combination with other biomarkers might be of clinical utility in assessing prostate cancer aggressiveness." (PMID 31606028, 2019). "This study suggests that PTPN12 expression may represent a useful prognostic biomarker in prostate cancer." (PMID 31606028, 2019). "Evidence suggests that PTPN12 expression might also be relevant for prostate cancer." (PMID 31606028, 2019). "For this purpose, a preexisting prostate cancer tissue microarray (TMA) consisting of more than 13,000 prostate cancers with clinical follow-up information and attached molecular data was examined for PTPN12 expression levels." (PMID 31606028, 2019).
bladder cancer (3 papers, 2021 to 2024). "PTPN12 depletion (shPTPN12) in the weakly metastatic breast and bladder cancer lines (UMUC3) increased ES-TF expression whereas PTPN12 transduction in 1833 decreased NANOG, MYC, and SOX2 expression." (PMID 38886396, 2024). "In addition, inhibition expression of PTPN12 remarkably enhances the proliferative, migratory, and invasive capacities of bladder carcinoma cells both in vitro and in vivo." (PMID 37333450, 2023).
nasopharyngeal carcinoma (3 papers, 2015 to 2022). A carcinoma arising from the nasopharyngeal epithelium. "The objective of this study was to investigate the clinicopathological and prognostic implication of PTPN12 in nasopharyngeal carcinoma (NPC) patients." (PMID 25663493, 2015). "Reduced PTPN12 expression may serve an important part in increased aggressiveness of nasopharyngeal carcinoma." (PMID 35290144, 2022).
angiosarcoma (2 papers, 2018 to 2019). A malignant tumor arising from the endothelial cells of the blood vessels. "This combination, and in particular inactivation of Ptpn12, was highly associated with the angiosarcoma phenotype in mice." (PMID 29872503, 2018). "Additional studies will focus on elucidating other critical substrates of PTPN12 loss in angiosarcoma which could lead to the identification of novel targets for therapy." (PMID 29872503, 2018). "This suggests a critical role for the Ptpn12 gene in tumor suppression with specificity for angiosarcoma." (PMID 29872503, 2018). "We analyzed the activation status of known PTPN12 substrates and RTKs expressed in vascular endothelial cells and several were found to be tyrosine phosphorylated in angiosarcoma." (PMID 29872503, 2018). "We found that PDGFR-β was phosphorylated in all three angiosarcoma models and was particularly prominent in Ptpn12; Pten DKO tumors in which this was the only RTK with elevated phosphorylation in the array." (PMID 29872503, 2018). "Intriguingly, we noted that the three cohorts of mice that developed angiosarcoma all include the deletion of Ptpn12." (PMID 29872503, 2018). "We first took a candidate approach to test whether RTKs involved in endothelial cell signaling and PTPN12 effectors are phosphorylated in angiosarcomas." (PMID 29872503, 2018). "While PTPN12 was not one of these genes, the number of angiosarcoma genomes that have been sequenced to date remains small." (PMID 29872503, 2018).
breast tumor (2 papers, 2013 to 2015). "PTPN12 co-precipitates with several other RTKs and was recently shown to dephosphorylate EGFR and HER2 in breast tumors, thereby inhibiting MAPK signaling." (PMID 23785422, 2013). "Furthermore, in the breast tumor MDA-MB-231 cells, PTPN12 silencing enhanced cell proliferation (unpublished results)." (PMID 25868976, 2015).
lymph node metastasis (2 papers, 2014 to 2019). "High PTPN12 staining was associated with high pT category, high classical and quantitative Gleason grade, lymph node metastasis, positive surgical margin, high Ki67 labeling index and early prostate specific antigen recurrence (p < 0.0001 each)." (PMID 31606028, 2019).
pancreatitis (2 papers, 2022 to 2025). Inflammation of the pancreas. "Five key factors were identified: Wdr1, Naa10p, Ptpn12, Upf1, and Ralb, all significantly upregulated in pancreatitis mice." (PMID 40557397, 2025). "In Logsdon dataset, we found that PTPN12 expressed significantly higher with a fold change of 4.631 in PAAD, and a fold change of 3.619 in pancreatitis versus normal samples." (PMID 35154122, 2022).
retinoblastoma (2 papers, 2021 to 2022). A malignant tumor that originates in the nuclear layer of the retina. "However, in retinoblastoma (RB), miR-503 was greatly expressed in RB tissues, and acted as an “onco-miR” by targeting PTPN12." (PMID 33762949, 2021).
squamous cell carcinoma (2 papers, 2015 to 2019). A carcinoma arising from squamous epithelial cells. "Although the population of our previous study limited to squamous cell carcinoma, our results suggested that PTPN12 might be served as a clinical predictive biomarker for various cancer populations." (PMID 25868976, 2015). "Patients with PTPN12-high tumors had a longer disease-free survival (DFS) (P<0.001) and overall survival (OS) (p<0.001), especially for those with non-squamous cell carcinoma (non-SCC) (DFS, p<0.001; OS, p<0.001)." (PMID 25868976, 2015).
acute myeloid leukemia (1 paper, 2022). Acute myeloid leukemia (AML) is a group of neoplasms arising from precursor cells committed to the myeloid cell-line differentiation. "Some classical PTPs exhibited carcinogenic features, such as PTPN12 in PAAD and PTPN6 in acute myeloid leukemia (LAML)." (PMID 36341348, 2022).
Alzheimer disease (1 paper, 2025). A progressive, neurodegenerative disease characterized by loss of function and death of nerve cells in several areas of the brain leading to loss of cognitive function such as memory and language. "In the case of the association between rs117934759 and PTPN12 expression in microglia (LRT—P = 1.72 × 10−16, q = 4.14 × 10−14), the eQTL association was strongly influenced by Alzheimer’s disease (AD) samples (ADinteraction, P = 1.11 × 10−10)." (PMID 39794547, 2025).
amyotrophic lateral sclerosis (1 paper, 2025). Amyotrophic lateral sclerosis (ALS) is a neurodegenerative disease characterized by progressive muscular paralysis reflecting degeneration of motor neurons in the primary motor cortex, corticospinal tracts, brainstem and spinal cord. "KEGG analysis revealed two processes, Huntington’s disease and Amyotrophic lateral sclerosis, whereas the REACTOM database revealed one item: EGFR downregulation, with three genes, protein-tyrosine phosphatase (PTP)-PEST (PTPN12), epidermal growth factor receptor (EGFR), and epsin 1 (EPN1)." (PMID 40269194, 2025).
autoimmune disease (1 paper, 2023). A disorder resulting from loss of function or tissue destruction of an organ or multiple organs, arising from humoral or cellular immune responses of the individual to their own tissue constituents. "PTPN12 is considered a promising therapeutic target for critical diseases such as cancer, diabetes, metabolic diseases, and autoimmune diseases and has been used for therapeutic intervention in acute myocardial infarction." (PMID 37884566, 2023).
Autoimmunity (1 paper, 2016). The occurrence of an immune reaction against the organism's own cells or tissues. "Also, PTPN12, inhibits secondary T‐cell responses and is implicated in human autoimmunity, which may have implications in those infected with HBV13." (PMID 27075395, 2016).
diabetic cardiomyopathy (1 paper, 2022). Diabetic cardiomyopathy is a disorder of the heart muscle in people with diabetes. "Overall, our study elucidated that downregulation of SFRP4 attenuated cardiomyocyte injury in H/R models and regulated the activation of the P13 K/AKT signaling pathway through PTPN12, which possibly provides a novel therapeutic target for patients with diabetic cardiomyopathy." (PMID 35290144, 2022).
glioma (1 paper, 2022). A benign or malignant brain and spinal cord tumor that arises from glial cells (astrocytes, oligodendrocytes, ependymal cells). "In addition, the mRNA expression of PTPN12 displayed a strong association with the advanced grade and short survival time in glioma." (PMID 36341348, 2022). "Further analysis found that PTPN12 was up-regulated in human glioma from TCGA and other independent datasets." (PMID 36341348, 2022). "We found that the overexpression of PTPN12 notably enhanced the growth velocity in different glioma cell lines, while PTPN12 silencing inhibited cell growth." (PMID 36341348, 2022). "To mechanically explore the functions of classical PTPs in shaping the TME, we evaluated the cancer immunity cycle process of PTPN12 in glioma." (PMID 36341348, 2022). "Taken together, these results suggest that PTPN12 is a potential oncogene in glioma and may be a promising target for glioma treatment." (PMID 36341348, 2022). "To better address whether PTPN12 was correlated with glioma tumorigenesis, we applied clinical specimens and observed that PTPN12 was significantly overexpressed in glioma samples contrasted with the paired adjacent samples at the protein level." (PMID 36341348, 2022). "Finally, we performed cell cycle and apoptosis analysis on PTPN12 in glioma cells." (PMID 36341348, 2022). "We found that PTPN12 could promote the proliferation and inhibit apoptosis of glioma cell lines." (PMID 36341348, 2022). "They found that, unlike epithelial cell-derived carcinomas, PTPN12 in glioma, primarily derived from neural stem cells, suppressed migration/invasion but promoted growth and viability even though EGFR and HER2 are hyperphosphorylated." (PMID 36341348, 2022). "Taking PTPN12 as an example, due to the significant correlation with cancer progression, we validated the potential function in glioma using GSEA and observed that PTPN12 contributed to several oncogenic pathways, including PI3K-AKT-mTOR signaling, and TNFα signaling." (PMID 36341348, 2022).
Insulin resistance (1 paper, 2019). Increased resistance towards insulin, that is, diminished effectiveness of insulin in reducing blood glucose levels. "Genes downregulated (n = 3) during the first ACTH response were associated with ECM remodeling and insulin resistance (ADAMTS9), cell growth and migration (ABI2), and negative regulation of tyrosine kinase activity (PTPN12)." (PMID 30804370, 2019).
invasive breast carcinoma (1 paper, 2025). A carcinoma that infiltrates the breast parenchyma. "Notably, PTPN12, identified as a tumor suppressor gene (TSG), exhibited upregulation in our DCIS samples—contrasting with its downregulation in invasive breast cancer (IBC)—indicating its potential as a predictive biomarker for DCIS progression." (PMID 41020869, 2025).
liver cancer (1 paper, 2024). An epithelial or non-epithelial malignant neoplasm that arises from the liver. "PTPN12 plays a crucial role in the progression of liver cancer and other cancers." (PMID 38992675, 2024).
liver fibrosis (1 paper, 2025). "Ptpn12 overexpression using an AAV6-Ptpn12 viral system alleviated CCl4-induced liver fibrosis in Srxn1fl/fl mice, but this protection was diminished in Srxn1ΔHSC mice." (PMID 41131335, 2025).
lung adenocarcinoma (1 paper, 2014). A carcinoma that arises from the lung and is characterized by the presence of malignant glandular epithelial cells. "In lung adenocarcinoma cell line NCI-H2009, a PTPN12 pseudogene caused an 8 kb target-site deletion that removed the promoter and first exon of MGA." (PMID 24714652, 2014).
melanoma (1 paper, 2015). A malignant, usually aggressive tumor composed of atypical, neoplastic melanocytes. "FlnA/PTPN12 interactions were then challenged in a pulldown assay using the interaction domain of PTPN12 fused to GST protein and melanoma cell lines stably expressing FlnA-WT and FlnA-P637Q." (PMID 26594644, 2015).
mitral valve prolapse (1 paper, 2015). A fairly common and often benign valvular heart disorder characterized by redundancy or hooding of mitral valve leaflets so that they prolapse into the left atrium, often causing mitral regurgitation. "Here, we have uncovered that the first eight repeats of FlnA constitute a binding site for PTPN12/PTP-PEST and showed that the FlnA mutations associated to mitral valve prolapse that specifically target this region disrupt PTPN12/FlnA interaction." (PMID 26594644, 2015).
multiple sclerosis (1 paper, 2022). A progressive autoimmune disorder affecting the central nervous system resulting in demyelination. "Notably, the PTPN22 gene, which is associated with SLE and multiple sclerosis susceptibility, belongs to the same family of PTPN12." (PMID 35743441, 2022).
pancreatic carcinoma (1 paper, 2022). "Besides that, Segara dataset and Pei dataset reported that the increased fold change of PTPN12 in pancreatic carcinoma versus normal samples are 2.448 and 2.210, respectively." (PMID 35154122, 2022).
pancreatic ductal adenocarcinoma (1 paper, 2022). An infiltrating adenocarcinoma that arises from the epithelial cells of the pancreas. "Furthermore, we found that PTPN12 overexpressed in pancreatic ductal adenocarcinoma with a fold change of 2.817 in Badea dataset." (PMID 35154122, 2022).
Peters anomaly (1 paper, 2024). Peters anomaly (PA) is a congenital corneal opacity disorder characterized by a central corneal leukoma that obstructs the pupil leading to visual loss as well as absence of the posterior corneal stroma and Descemet membrane. "Our results demonstrate that Abl kinases regulate FGF signaling to balance RhoA and Rac1 activity via the Ptpn12-p130Cas pathway, suggesting that targeting tension-mediated lens vesicle separation could be a therapeutic strategy for Peters anomaly." (PMID 39484567, 2024).
squamous cell lung carcinoma (1 paper, 2023). A carcinoma arising from squamous bronchial epithelial cells. "A study shows that the expression of PTPN12 is much lower in non-squamous cell lung cancer tissues than in normal lung tissues; high expression of PTPN12 predicts longer disease-free survival and overall survival." (PMID 37333450, 2023).
viral infections (1 paper, 2012). "However, all except PTPN12 are associated with other viral infections." (PMID 23240068, 2012). "The only protein identified in the TNF alpha hub that was down-regulated, namely PTPN12, is also the only protein that has not yet been reported in any other viral infections to date." (PMID 23240068, 2012).